OR4M1 (olfactory receptor family 4 subfamily M member 1)
Description:
Olfactory receptor that acts as a receptor of Asprosin hormone, potentially at the surface of hepatocytes and may help to promote hepatocyte glucose release.
Synonyms: OLFR734; OR14-7
Tractability: Antibody: UniProt places it where antibodies can reach, with high confidence; its Gene Ontology location is reachable by antibodies, with high confidence; UniProt predicts a signal peptide or a membrane-spanning region.
Gene: Protein-coding gene on chromosome 14 (19,773,504 to 19,783,696, forward strand). Ensembl gene ENSG00000176299.
Subcellular location: Cell membrane
Pathways (Reactome):
Sensory Perception: Expression and translocation of olfactory receptors
Gene Ontology:
Molecular function: olfactory receptor activity; G protein-coupled receptor activity
Biological process: detection of chemical stimulus involved in sensory perception of smell; G protein-coupled receptor signaling pathway
Cellular component: plasma membrane; membrane
Genetic constraint (gnomAD): Loss-of-function variants: 10 observed, 13.25 expected, observed/expected ratio (o/e) 0.75, 90% interval 0.47 to 1.28. The upper end of that interval is the gene's LOEUF score, 1.28, which puts it in group 5 of 6, group 1 being the genes least tolerant of losing a copy. Missense variants: 331 observed, 331.21 expected, observed/expected ratio (o/e) 1, 90% interval 0.91 to 1.1. Synonymous variants: 121 observed, 120.21 expected, observed/expected ratio (o/e) 1.01, 90% interval 0.87 to 1.17.
Homologues: Orthologues: macaque OR4M1 (97% identical), rat Or4m1 (92% identical), mouse Or4m1 (91% identical). Paralogues in human: OR4M2 (94% identical), OR4M2B (93% identical), OR4N5 (58% identical), OR4N2 (54% identical), OR4N4C (53% identical), OR4N4 (53% identical), OR4K1 (50% identical), OR4Q3 (49% identical), OR4K15 (49% identical), OR4K14 (48% identical), OR4S1 (48% identical), OR4S2 (48% identical), and 116 more.
Diseases named in the same sentence as OR4M1 in open-access papers:
OR4M1 is named in the same sentence as 14 diseases in open-access papers, as found by Europe PMC text mining. Sharing a sentence is not in itself a finding about the gene and the disease. The quoted sentences say what the papers report.
ovarian carcinoma (3 papers, 2021 to 2025). A malignant neoplasm originating from the surface ovarian epithelium. "Previous work from our group has also shown that OR4M1 is expressed in the ovaries and is upregulated in early stages of ovarian cancer (I and II) compared to late ones (III and IV)." (PMID 40871563, 2025). "Our group has shown that OR4M1 is upregulated in ovarian cancer, particularly at early stages (I and II) compared to late stages (III and IV)." (PMID 38339334, 2024). "We then measured expression of FBN1 and OR4M1 in five ovarian cell lines: one normal ovarian epithelial cell line (HOSEpiC), and four ovarian cancer cell lines namely, SKOV-3, PEO1, PEO4 and MDAH-2774." (PMID 34386072, 2021). "Observations on the expression of asprosin and OR4M1 were expanded using the SKOV-3 ovarian cancer cell line, as well as the normal human ovarian epithelial cell line, HOSEpiC (OSE)." (PMID 34386072, 2021). "In conclusion, to the best of our knowledge, this is the first study to demonstrate expression of asprosin and its cognate receptor, OR4M1, in the human ovaries in health and cancer, focusing specifically on ovarian cancer." (PMID 34386072, 2021). "The present study investigated the expression levels of the glucogenic hormone asprosin [encoded by fibrillin-1 (FBN1)], and its cognate receptor, olfactory receptor 4M1 (OR4M1), in ovarian cancer." (PMID 34386072, 2021). "To that aim and following studies on the expression in normal murine and bovine ovaries, we provide novel data regarding the expression of both asprosin and its cognate receptor, OR4M1, in normal human ovaries and ovarian cancer." (PMID 34386072, 2021). "In addition, OR4M1 expression was significantly up regulated in the same ovarian cancer samples (n=12) compared to the controls (n=6)." (PMID 34386072, 2021). "Immunohistochemical staining of a tissue microarray was used to identify the expression levels of OR4M1 and asprosin in ovarian cancer samples of varying histological subtype and grade, including clear cell carcinoma, serous ovarian cancer and mucinous adenocarcinoma." (PMID 34386072, 2021). "This study presents novel data regarding the expression of FBN1 (the gene encoding profibrillin-1), asprosin (the novel orexigenic/glucogenic hormone which is cleaved from profibrillin-1), and OR4M1 (the human cognate receptor of asprosin) in cancer, focusing on ovarian cancer." (PMID 34386072, 2021). "RT-qPCR revealed expression levels of OR4M1 and FBN1 in clinical samples and in ovarian cancer cell lines (SKOV-3, PEO1, PEO4 and MDAH-2774), as well as the normal human ovarian surface epithelial cell line (HOSEpiC)." (PMID 34386072, 2021). "FBN1 was significantly over-expressed in HOSEpiC cells compared to all studied ovarian cancer cell lines, whereas no apparent change in the expression of OR4M1 was noted across all five cell lines." (PMID 34386072, 2021). "Immunohistochemical analysis of a tissue microarray containing 90 ovarian cancer cores and 10 normal adjacent tissue (NAT) cores, each representing a different clinical case, was used to measure the protein expression of asprosin and OR4M1." (PMID 34386072, 2021). "Moreover, the samples of ovarian cancer where RT-qPCR was performed were all stage III/IV, as such we do not have the data to compare mRNA expression of FBN1 and OR4M1 in early stages of ovarian cancer." (PMID 34386072, 2021).
Insulin resistance (2 papers, 2022 to 2025). Increased resistance towards insulin, that is, diminished effectiveness of insulin in reducing blood glucose levels. "It stimulates hepatic glucose production via the G protein-coupled receptor (GPCR)-activated cAMP signaling pathway olfactory receptor family 4 subfamily M member 1 (OR4M1) and is correlated with insulin resistance." (PMID 35456360, 2022).
liver disease (1 paper, 2025). "Given the significant influence of gender on liver disease and various metabolic pathway disorders, we stratified our data by sex to determine whether OR4M1 expression exhibits a similar pattern in both sexes." (PMID 40806011, 2025).
liver steatosis (1 paper, 2025). "In conclusion, this study is the first to (i) investigate the modulation of Olfr734 in the development of MASLD; (ii) establish a link between asprosin signaling-induced liver steatosis and a Sirt/ER stress pathway; and iii) associate the hepatic levels of OR4M1 with patients with T2DM." (PMID 40806011, 2025).
Obesity (1 paper, 2025). Accumulation of substantial excess body fat. "To investigate this, we measured the levels of the human gene encoding the asprosin receptor, OR4M1, in the livers of patients with obesity, both normoglycemic and with T2DM." (PMID 40806011, 2025). "Our analysis revealed that the mRNA levels of OR4M1 are elevated in patients with obesity and T2DM compared to those with obesity and normoglycemia." (PMID 40806011, 2025). "Furthermore, to assess the translational relevance of our findings, we demonstrated that the human hepatic Olfr734 ortholog, OR4M1, is present at significantly higher levels in male patients with obesity and T2DM compared to those with obesity and normoglycemia." (PMID 40806011, 2025).
ovarian tumour (1 paper, 2021). "This research invokes further investigation to advance the understanding of the role of asprosin and OR4M1 within the ovarian tumour microenvironment." (PMID 34386072, 2021).
cancer (4 papers, 2021 to 2025). A tumor composed of atypical neoplastic, often pleomorphic cells that invade other tissues. "No significant changes in the expression of protein tyrosine phosphatase receptor type D (PTPRD) and olfactory receptor family 4 subfamily M member 1 (OR4M1) were observed amongst those with EC versus non-cancer controls (P=0.044 and P=0.221, respectively)." (PMID 40902078, 2025). "Previously published work by our research group has explored the role of asprosin in cancer by studying asprosin and its proposed cognate receptor Olfactory Receptor Family 4 Subfamily M Member 1 (OR4M1)." (PMID 38339334, 2024). "Here, using liquid biopsies from OvCa patients, we demonstrate novel expression of both OR4M1 and TLR4 in cancer-associated circulating cells (CCs) of patients with high grade serous OvCa, with a significant decline in OR4M1 positive cells seen between pre-chemotherapy and treatments." (PMID 36233808, 2022).
OR4M1 also shares sentences with these, for which no sentence is quoted: bipolar disorder (1 paper); clear cell carcinoma (1); Hyperglycemia (1); metabolic disease (1); mucinous adenocarcinoma (1); serous ovarian cancer (1); steatosis (1).